CD36 (CD36 molecule (CD36 blood group))
Diseases named in the same sentence as CD36 in open-access papers (continued):
Sharing a sentence is not in itself a finding about the gene and the disease.
tumor (continued). "Finally, we used the TCGA HCC dataset to assess the influence of stratification of tumor samples based on low or high CD36 expression clusters and low (<25) or high BMI (≥30) groups." (PMID 26424075, 2015). "Thus, the reduction found in whole tumour Cd36 expression is likely to be due to deregulation in the stroma, as suggested previously." (PMID 25633981, 2015). "CD36 is an 88-kDa integral plasma membrane protein and is expressed by a variety of cells including platelets, erythrocytes, endothelial cells, monocytes, granulosa, theca, and tumour cells." (PMID 24628875, 2014). "CD36 has been shown to be required for the anti-angiogenic activity of these proteins and is absence impairs their angiogenesis inhibition and tumor vascularity increases and tumor growth is accelerated." (PMID 24628875, 2014). "We thus hypothesized that accumulation of HRG in the tumor microenvironment would promote tumor growth, similar to loss of tumor cell TSR expression, and that down-regulation of the receptor, CD36 would have an opposite effect." (PMID 22808089, 2012). "LL2 tumor volumes were greater in cd36 null mice and smaller in hrg null mice compared to WT." (PMID 22808089, 2012). "For instance, TNBC's unique metabolic demands, driven by glycolytic dominance rather than lipid dependency, might render CD36 loss advantageous for tumor progression, whereas lipid‐rich luminal/HER2+ microenvironments could exploit CD36‐mediated FA transport to fuel metastatic growth." (PMID 41267927, 2025). "Indeed, we found that CD36 was highly expressed in the BCSC population with the CD44High/CD24Low phenotype compared with the bulk cell population, while ALDH + cells exhibited lower levels of CD36 expression than did the total differentiated/bulk tumor cell population." (PMID 39833955, 2025). "CD36 is strongly linked to immune regulation, as evidenced by its association with diverse immune infiltrates, enrichment in TGF-β–dominant and inflammatory subtypes, and correlation with key steps of the cancer immune cycle, highlighting its role in remodeling the tumor-immune microenvironment." (PMID 41550652, 2025). "However, the expression of TSP-1 receptor CD36 is preserved or even elevated in tumor cells, which may be due to the fatty acid metabolism mediated by CD36 supporting tumor growth in metastatic sites such as omentum." (PMID 40801564, 2025). "Moreover, another finding showed that CD36 mediated tumor-infiltrating CD8+ T cells in tumor microenvironment could induce lipid peroxidation and ferroptosis, thereby reducing cytotoxic cytokine production and impairing antitumor ability." (PMID 41285711, 2025). "For example, CD36, a scavenger receptor, facilitates metabolic crosstalk between macrophages and cancer cells by uptaking tumor cell-derived extracellular vesicles enriched in long-chain fatty acids, which enhances their tumor-promoting potential and contributes to a pro-metastatic environment." (PMID 40625731, 2025). "Additionally, CD36+ TAMs exhibit elevated levels of interleukin-10 (IL-10) and growth factors, indicative of their anti-inflammatory phenotype and potential role in promoting tumor progression." (PMID 41341850, 2025). "Indeed, blockade of free fatty acid release by tumor cells or free fatty acid uptake by Treg cells (via anti-CD36 antibody treatment or Treg cell-specific deletion of CD36) decreases intratumoral Treg cell accumulation and reverses tumor resistance to anti-PD-1 treatment." (PMID 40468052, 2025). "Beyond classical role of lipid uptake and fatty acid oxidation (FAO) in metastasis and therapy resistance, CD36 also contributes to angiogenesis, T-cell metabolism, and macrophage polarization, positioning it as a bridge between intrinsic and microenvironment of tumor cells." (PMID 41550652, 2025).
tumor (continued). "CD36 is a B2 receptor of the scavenger receptor class B family and is composed of single-chain secondary transmembrane glycoproteins; it is expressed in cancer cells, stromal cells and immune cells, but its expression varies among distinct cell types and tumor stages." (PMID 39984452, 2025). "Similarly, targeting the CD36 fatty acid transporter with monoclonal antibodies has been demonstrated to effectively block fatty acid uptake and lipid metabolism in tumor-infiltrating Tregs, hindering their accumulation and function in melanoma models without causing systemic loss of Tregs." (PMID 40051496, 2025). "Because VT1021 does not target a specific mutation in tumor cells but rather induces TSP-1 that inhibits tumor growth via binding to CD36 and CD47 on the surface of tumor cells, it is critical to identify patients that express sufficient levels of these receptors to maximize its anti-tumor activity." (PMID 39627379, 2024). "Additionally, the protein levels of CPT1 and CD36 were decreased in MMP-12-knockdown tumor cells." (PMID 38511770, 2024). "We hypothesize that when patients with heterogeneous tumor cell expression of CD36/47 are treated with VT1021, tumor cells with high CD36 and CD47 would be killed, but tumor cells with low levels of CD36 and CD47 would not respond to the VT1021 treatment, resulting in a lack of response." (PMID 39627379, 2024). "CD36 inhibition not only disrupts Tregs mitochondrial functionality but also augments ferroptotic sensitization in neoplasms through lactic acid attenuation, while HIFs inhibition prevents the pro-tumor polarization of TAMs, simultaneously reducing neoplastic ferroptotic resistance." (PMID 38217037, 2024). "Because the synergistic effect of CD36 inhibitors and immunotherapy has generated much interest as a new therapeutic strategy, CD36 may be a potential therapeutic target for cancer therapy as a central regulator for tumor progression and immune evasion in tumor-bearing hosts." (PMID 39273384, 2024). "However, they outline a new link between increased CD36 gene methylation and tumor development." (PMID 38370376, 2024). "We chose multiple FOVs (n = 36 annotated and classified) from two samples, each from LN (normal), SLN (−), and SLN (+), and leveraged an MxIF spatial analysis to understand whether CD36 is overexpressed in the presence of tumor cells in SLN+ or EVs itself directed modification in SLN (−) tissue." (PMID 39062552, 2024). "Therefore, CD36 has different effects on tumor cells and cells in the tumor microenvironment (TME)." (PMID 38276607, 2024). "Therefore, preventing CD36 expression or interfering with its function might become a treatment for tumors or, particularly, an effective strategy for inhibiting tumor metastasis." (PMID 38276607, 2024). "Thus, one potential therapeutic strategy could focus on CD36 inhibition to target the tumor-macrophage metabolic interface." (PMID 38370376, 2024). "However, recent studies have also focused on the pro-tumor roles of CD36." (PMID 39273384, 2024). "Consequently, it could be interesting to investigate further if CD36 expression is influenced by hypoxia in the tumor environment." (PMID 38370376, 2024). "Thus, we investigated whether tumor cell expression at the invasive front of the proteins CD36, FABP4, and ANGPTL4, which are involved in the release, cellular uptake, and transport of fatty acids differs between normal and overweight/obese TNBC patients." (PMID 39456610, 2024). "Using both CD36 inhibitors and anti-PD-1 could enhance the anti-tumor effects." (PMID 38264667, 2023). "Moreover, recent studies also unraveled pro-tumor roles of CD36 on immune cells in the TME." (PMID 37207149, 2023). "Therefore, combination of other therapies including chemotherapy and CD36 blockage could promisingly enhance anti-tumor effects in NSCLC." (PMID 37085798, 2023).
tumor (continued). "Importantly, these results suggest that CD36+ CAFs may facilitate the acquisition of certain tumor-promoting functions in MDSCs via paracrine signaling." (PMID 36878933, 2023). "Moreover, when analyzing immune infiltration status, we found that the CD36 expression level was negatively related to CD8+ T cells, which indicated that CD36+ tumor cells could promote tumor progression by exhibiting immune infiltration." (PMID 37207149, 2023). "Therefore, CD36 played an important role in lipid homeostasis and tumor metastasis." (PMID 37978381, 2023). "Therefore, the targeting CD36 can inhibit the absorption of tumor cells and metastasis." (PMID 36721212, 2023). "Thus, the depletion of CD36 can result in the apoptosis of Tregs with decreasing tumor growth." (PMID 36721212, 2023). "Therefore, Treg-specific CD36 knockout or treatment with a function-blocking antibody suppressed tumor growth and promoted anti-tumor immunity, which was even more pronounced when it was combined with an immune checkpoint inhibitor, such as an anti-PD-1 antibody." (PMID 37371076, 2023). "In addition, we noticed that the expression of CD36 in CD8+ T cells was higher than tumor cells." (PMID 37085798, 2023). "In contrast, it has been demonstrated that CD8+ tumor-infiltrating lymphocytes were shown to have reduced anti-tumor function, which is attributed to an increase in lipid peroxidation resulting from the uptake of fatty acids and oxidized lipids mediated by CD36." (PMID 38060103, 2023). "Moreover, in an in vivo model, blocking of CD36 led to a reduction in tumor growth." (PMID 35625629, 2022). "Although it remains unclear how expression of CD36 on tumor-infiltrating T cells is regulated, this tissue selectivity provides a unique opportunity to develop promising strategies for metabolically targeting TME without significantly altering systemic tissue homeostasis." (PMID 35438721, 2022). "Furthermore, specific targeting of CD36 in cancer cells using phage-display may be an approach to interfere with tumor lipid metabolism, hence making chemotherapy more effective." (PMID 35991116, 2022). "CD36, also known as fatty acid translocase (FAT), FA transport protein family (FATPs), solute carrier protein family 27 (SLC27), and plasma membrane fatty acid-binding proteins (FABPpm) are discovered to be highly expressed in tumours and are implicated in the FA de novo synthesis." (PMID 36816174, 2022). "Therefore, anti-CD36 monoclonal antibody treatment reveals profound effects on inhibiting melanoma tumor growth in the recipient mice, accompanied by induction of Treg cell apoptosis, enhanced CD8+ T cell infiltration, and higher cytokine production in CD4+ and CD8+ TILs." (PMID 39872079, 2022). "Moreover, CD36 expressed by CD8+ T cells leads to an accumulation of lipid peroxides in CD8+ T cells through the uptake of fatty acids in the tumour environment, which in turn leads to an elevated iron ion content, increased ferroptosis processes, and reduced secretion of cytotoxic cytokines." (PMID 35295858, 2022). "Nur77, a tumor suppressor, inhibits breast cancer cells from uptaking exogenous fatty acids and blocks the accumulation of fatty acids in the tumor metabolic microenvironment by inhibiting the transcription of the transmembrane protein CD36 and the cytoplasmic fatty acid-binding protein FABP4." (PMID 36611922, 2022). "Moreover, CD36 expression on tumour-infiltrating Treg cells may mediate the uptake of long-chain fatty acids." (PMID 36569832, 2022). "Therefore, CD36-mediated tumor VM may have great research potential in the future, and characterization of the specific underlying mechanism will provide a theoretical basis for the function of CD36 in regulating tumor vasculature." (PMID 36354702, 2022). "Therefore, targeting CD36 and ferroptosis may be an effective strategy to improve the anti-tumor efficacy of T cell-based immunotherapy." (PMID 36387286, 2022).
tumor (continued). "We then investigated whether factors secreted from CD36+ FBs might exert anti-tumor effects." (PMID 36361532, 2022). "Furthermore, CD36 targeting may be affecting not only CD36+ cancer cells but also stromal or infiltrating tumor cells." (PMID 36568966, 2022). "Additionally, high expression of CD36 in tumor cells was also found to predict poor prognosis." (PMID 36354702, 2022). "However, CD36 expression in CAFs was also found to enhance tumor progression." (PMID 36354702, 2022). "Studies suggest that CD36-mediated efferocytosis or phagocytosis may participate in DC presentation of tumor antigens, viral antigens, and malarial antigens through both MHC class I and class II systems, and therefore may play a role in modulating T cell and B cell responses." (PMID 35438721, 2022). "Flow cytometry analysis of tumor-treated BMDMs showed a decreased percentage of antitumor M1-type macrophages (CD206lowCD80high), but an increased presence of protumor M2-type macrophages (CD206highCD80low), which could be largely abrogated by CD36 deletion." (PMID 36184646, 2022). "Moreover, CD36 knockdown repressed the tumor growth and extended the survival in a HER2+ BC model." (PMID 35800378, 2022). "In addition, targeting CD36 enhanced the anti-tumor activity by reducing the effects of Tregs." (PMID 35812393, 2022). "In tumor mice, an antibody targeting CD36 showed that 15% of metastases (lymph node and lung metastases) achieved a complete response (CR), and mice that had developed lymph node metastases had an 80–90% reduction in lesion size, with little effect on the primary tumor." (PMID 35833121, 2022). "However, within the tumor microenvironment, it is also important to show whether these three recombinant proteins, secreted from CD36+ FBs, can also revert CD36 in CAFs." (PMID 36361532, 2022). "CD36-targeted therapies, including CD36 neutralizing antibodies, have been in development, but knowledge gaps about the multiple roles of this protein in cancer cells as well as in the tumor microenvironment must be filled before further advancements can be made towards clinical practice." (PMID 35008415, 2022). "In addition to directly eliminating tumor cells, CD36 inhibition could refine the immunosuppressive TME and suppress tumor progression by ablating the function of intra-tumor Tregs." (PMID 34742349, 2021). "Targeting CD36 may have a potential for therapy, which will target the tumour microenvironment." (PMID 34561446, 2021). "This prompted us to think about whether CD36 may orchestrate glucose metabolism in tumor cells." (PMID 33771982, 2021). "In addition, changes in the transport of cholesterol, also regulated by CD36, could affect tumor growth." (PMID 34314388, 2021). "Hence, these genes might serve as molecular targets to restrict oncogenic (i.e. ATIC, BZW2) and lipogenic (i.e. CD36, PPARγ), but promote tumor suppressive (i.e. TAGLN2) activity to treat human HCC." (PMID 32559205, 2020). "Thus, CD36 may promote tumor progression by cross-talking with signaling pathways such as ERK, and therefore targeting CD36 in cancer could be a promising strategy." (PMID 32046099, 2020). "However, for PC was reported that CD36 is required on immune cells, to allow extravasation of tumor microvesicles from premetastatic foci, while it seems that CD36 may also act as a tumor-suppressive protein, since it appears downregulated on PC cells." (PMID 32781778, 2020). "However, its roles in tumors are far more contentious, even in the same cancer type, CD36 could be either oncogenic or tumor suppressive." (PMID 31484922, 2019).
tumor (continued). "Further investigations are warranted to ascertain whether miR also contributes to a tumor metastatic property via CD36 and how the CD36-mediated miR–lipoprotein complex internalization shuttles miR to the RNA-induced silencing complex to elicit their gene regulatory effects." (PMID 30850595, 2019). "Thus, LPA derived from activated tumor cells might regulate CD36 in adjacent or distant target cells." (PMID 31410189, 2019). "Apoptotic tumor cells release various factors including long-chain free fatty acids and oxidized phospholipids, which may also act as carriers of miR-375 for CD36-mediated uptake, as they are known ligands of CD36." (PMID 31766495, 2019). "Hence, we selected C33a, HeLa, and SiHa cells to study whether CD36 exerted tumor-promoting effects by assaying for cell migration, invasion, proliferation, and apoptosis." (PMID 31655604, 2019). "Anti-CD36 decreased the tumor-promoting effects of PA in GC cells with basal level or overexpression of CD36 but not with silenced CD36, further supporting the hypothesis that CD36 contributed to the metastasis of GC by taking up exogenous PA." (PMID 30717785, 2019). "However, the effect of CD36 palmitoylation in tumor cells remains to be investigated." (PMID 31410189, 2019). "Interestingly, tumor metastasis was augmented by a fat rich diet, in a CD36-dependent manner." (PMID 31769430, 2019). "This hypothesis was confirmed by normal expression of CD36 on isolated tumour cells." (PMID 30069479, 2018). "Our data suggest that tumor cells could induce a state of functional TSR deficiency and hence promote angiogenesis and tumor growth) by remodeling their micro-environment to down-regulate microvascular CD36 expression and/or up-regulate accumulation of HRGP." (PMID 22808089, 2012). "The tumor microenvironment generates an abundance of oxidized low‐density lipoproteins (ox‐LDL), which are taken up by CD8+ T cells expressing high levels of CD36." (PMID 41560416, 2026). "This systematic review synthesizes the mechanisms by which CD36 contributes to NSCLC proliferation, migration, epithelial-mesenchymal transition, and modulation of the tumor microenvironment." (PMID 41595136, 2026). "A significant down-regulation of CD36, FABP4, PLIN1, SCD5 and ACSL4 in tumor samples has also been validated by RT-qPCR." (PMID 40860798, 2025). "Increased CD36 attenuates the ability of CD8+ T cells to release cytotoxic factors and promote tumor progression." (PMID 39984452, 2025). "At the same time, the high expression of CD36 also enables TSP-1 to bind with it specifically, which triggers downstream apoptotic signaling pathways, promoting tumor cell apoptosis." (PMID 40801564, 2025). "CD36-mediated ferroptosis inhibits and impairs the antitumor function of CD8 T cells within the tumor and promotes the development of HCC." (PMID 39774047, 2025). "Normal mammary fat pads (MFPs) and tumor sections (n = 5 per group) were double-stained for Lyve-1 to identify single M-LECP cells and eight proteins known to promote cell fusion including CD36, CD98, CD209, Dap12, Dc-stamp, Sirp-a, Sirp-b1, and stabilin-1." (PMID 40507286, 2025). "In CRC, FABP4, together with CD36 and SCD, mediates fatty acid uptake in tumor cells, promoting liver and lung metastasis." (PMID 40717587, 2025). "It has been reported that CD36 is the main effector of the S100A4/PPAR-γ pathway, and its mediated fatty acid uptake plays an important role in the tumor-promoting function of macrophages." (PMID 40658605, 2025). "In conclusion, our study provides compelling evidence that tumor-derived SAA suppresses anti-tumor immunity by impairing APC activation and antigen presentation via CD36, thus hindering CD8+ T cell-mediated cytotoxic responses." (PMID 41488634, 2025). "Among the most established biomarkers are members of the scavenger receptor family, such as CD206, CD163, stabilin-1, Marco, CD36, and CD204, which are expressed on CD68+ macrophages in tumor tissues." (PMID 41417432, 2025).